PRKCZ (protein kinase C zeta)
Diseases named in the same sentence as PRKCZ in open-access papers (continued):
Sharing a sentence is not in itself a finding about the gene and the disease.
psoriasis (2 papers, 2019 to 2020). An autoimmune condition characterized by red, well-delineated plaques with silvery scales that are usually on the extensor surfaces and scalp. "BAIAP2 has been shown to control the expression of the proinflammatory cytokines IL-6 and IL-1α, and PRKCZ has been noted to play a role in controlling inflammatory dermal mesenchymal stem cells in psoriasis, a T cell-mediated disease." (PMID 32117236, 2020).
rheumatoid arthritis (2 papers, 2020). A chronic, systemic autoimmune disorder characterized by inflammation in the synovial membranes and articular surfaces. "It is believed that the activation of PRKCZ leads to the production of reactive oxygen species and facilitates osteoclast differentiation in synovium tissue of patients with rheumatoid arthritis." (PMID 32496000, 2020).
schizophrenia (2 papers, 2020 to 2022). A major psychotic disorder characterized by abnormalities in the perception or expression of reality. "Some of the connected genes like PRKCZ, SHANK2, ZNF608, and PRDM16 were also identified as schizophrenia risk factors." (PMID 36259657, 2022).
Stroke (2 papers, 2019 to 2023). Sudden impairment of blood flow to a part of the brain due to occlusion or rupture of an artery to the brain. "Using a pathway analysis, we found deletions in GNB1, PRKCZ, and GNG7 genes related to the alpha-adrenergic receptor signaling pathway that play a major role in determining the risk of an AF-related stroke." (PMID 30857284, 2019).
acute coronary syndrome (1 paper, 2021). Signs and symptoms related to acute ischemia of the myocardium secondary to coronary artery disease. "PRKCZ DNA methylation was identified as a potential epigenetic-sensitive target in acute coronary syndrome via network analysis." (PMID 35174173, 2021).
acute monocytic leukemia (1 paper, 2015). Acute monoblastic leukemia (AML-M5), is one of the most common subtypes of acute myeloid leukemia (AML) that is either comprised of more than 80% of monoblasts (AML-M5a) or 30-80% monoblasts with (pro)monocytic differentiation (AML-M5b). "The endogenous PRKCZ transcript and protein levels were low for both SKOV3 and OVCAR3 compared to THP-1 cells, a human acute monocytic leukemia cell line that expresses high endogenous levels of PRKCZ." (PMID 25874946, 2015).
Allergy (1 paper, 2015). An allergy is an immune response or reaction to substances that are usually not harmful. "PRKCZ in cord blood T cells has been associated with allergy risk in infants and it has been reported that gender differences affect susceptibility to the development of hypersensitivity reactions." (PMID 26419829, 2015).
Arrhythmia (1 paper, 2025). Any cardiac rhythm other than the normal sinus rhythm. "Lastly, based on our observations in SANAD, we note that variation in some genes like PRKCZ or TRDN may lead to susceptibility of secondary symptoms (in epilepsy or other neurodevelopmental disorders) e.g., memory loss or arrhythmia." (PMID 41345172, 2025).
atrial fibrillation (1 paper, 2024). A disorder characterized by an electrocardiographic finding of a supraventricular arrhythmia characterized by the replacement of consistent P waves by rapid oscillations or fibrillatory waves that vary in size, shape and timing and are accompanied by an irregular ventricular response. "Another study found that the deletion of the PRKCZ gene in a genome-wide association study increased the risk of thromboembolic stroke in patients with atrial fibrillation." (PMID 39065726, 2024).
centronuclear myopathy (1 paper, 2024). Centronuclear myopathy (CNM) is an inherited neuromuscular disorder characterized by clinical features of a congenital myopathy and centrally placed nuclei on muscle biopsy. "Moreover, SPEG is linked to centronuclear myopathy, while PRKCZ is associated with adenocarcinoma of the large intestine." (PMID 39434882, 2024).
end-stage renal disease (1 paper, 2024). "The most common non-HLA antibodies were anti-ENO1 (28.4%), anti-FIBR1 (23.0%) and anti-PRKCZ (23.0%), indicating their possible involvement in the immune responses of patients with end-stage renal disease on the kidney transplant waiting list." (PMID 39596170, 2024).
esophageal adenocarcinoma (1 paper, 2017). A malignant tumor with glandular differentiation arising predominantly from Barrett mucosa in the lower third of the esophagus. "Copy number alterations were also analyzed among esophageal adenocarcinoma, which showed that SKI and PRKCZ, biomarkers involved in transforming growth factor-β pathway, were located at a deletion region, suggesting the potential utility of novel biomarkers for EA29." (PMID 28169357, 2017).
glioblastoma (1 paper, 2015). The most malignant astrocytic tumor (WHO grade IV). "For example, it was reported that PRKCZ expression level is two fold higher in glioblastoma cell lines compared with normal astrocytes." (PMID 25874946, 2015).
gout (1 paper, 2021). A condition characterized by painful swelling of the joints, which is caused by deposition of urate crystals. "5'UTR hypomethylation is associated with gene upregulation, and hypomethylated PRKCZ might therefore increase PRKCZ expression, subsequently increasing IL-1β production in macrophages and facilitating gout." (PMID 33493135, 2021). "The results indicated that hypomethylation in PRKCZ and STK11 was associated with familial clustering of gout." (PMID 33493135, 2021). "Decreases in PRKCZ and STK11 methylation were also associated with higher numbers of first-degree relatives who also had gout." (PMID 33493135, 2021). "Moreover, PRKCZ and STK11 methylation was also associated with familial clustering of gout." (PMID 33493135, 2021). "Finally, decreased PRKCZ and STK11 methylation were associated with familial clustering of gout." (PMID 33493135, 2021). "Interesting, methylation levels of PRKCZ and STK11 were lower for individuals with more extensive family histories of gout in first-degree relatives." (PMID 33493135, 2021). "The final nine surviving monocyte-specific differentially methylated CpG sites were mapped to eight genes (PRKCZ, CIDEC, VDAC1, CPT1A, BIRC2, BRCA1, STK11, and NLRP12) that have not previously been studied in the field of gout genetics." (PMID 33493135, 2021).
inflammatory breast carcinoma (1 paper, 2023). An advanced, invasive breast adenocarcinoma characterized by the presence of distinct changes in the overlying skin. "Macrophage M2 polarization was inhibited by PM37, and radiation resistance of IBC (inflammatory breast cancer) was prevented by down-regulating PRKCZ." (PMID 36980514, 2023).
intestinal cancer (1 paper, 2016). "Intestinal cancer driven purely by PTEN-deficiency in transgenic mice developed CM and in human CRC, CM associated with PTEN and PRKCZ readouts." (PMID 27119498, 2016).
lymph node metastasis (1 paper, 2022). "In addition, PRKCZ hypermethylation was associated with the pathological grade of HNSCC patients, but not with sex, age, T stage, lymph node metastasis, or tumor recurrence." (PMID 36077689, 2022).
nephrolithiasis (1 paper, 2021). The presence of a calculus in the pelvis of the kidney; this is most often composed of mineral salts and proteins. "Genes in this crosstalk include those previously reported to be of functional relevance to nephrolithiasis, such as protein kinase C (PRKCA, PRKCB, and PRKCZ), markers (CD40 and TLR3), and autophagy (MTOR and SQSTM1), thus validating our genetic prioritization at the gene and pathway level." (PMID 34489936, 2021).
osteosarcoma (1 paper, 2020). A usually aggressive malignant bone-forming mesenchymal neoplasm, predominantly affecting adolescents and young adults. "In addition, PRKCZ is a potential prognosis marker for patients with osteosarcoma." (PMID 32496000, 2020).
pancreatic adenocarcinoma (1 paper, 2010). "Herein, we demonstrate a critical role for RHOA and PRKCZ in the regulation of different aspects of cell motility of pancreatic adenocarcinoma and demonstrate the need to inhibit both pathways to obtain a functionally relevant effect in most assays." (PMID 20236512, 2010).
pheochromocytoma (1 paper, 2019). "Similarly, mutations only associated with pheochromocytoma severely affect the DGKZ, PRKCI, PRKCD and PRKCZ kinase binding interfaces, further suggesting a link between hypoxia sensing and phosphorylation-mediated signaling." (PMID 30943211, 2019).
tuberculosis (1 paper, 2023). A chronic, recurrent infection caused by the bacterium Mycobacterium tuberculosis.
cancer (19 papers, 2010 to 2025). A tumor composed of atypical neoplastic, often pleomorphic cells that invade other tissues. "Whether the effect of PRKCZ on some important tumor stromal cells, such as cancer-associated fibroblasts, can affect or even counteract its effect on tumor cells, which needs further research." (PMID 36077689, 2022). "PRKCZ has been considered a significant mediator with a tumor-promoting or tumor-suppressing role in different cancers." (PMID 36077689, 2022). "The monoallelic loss was most prevalent in PRKCD, then PRKCH, PRKCZ, and PRKCQ across many cancer types compared to other genes." (PMID 35174160, 2021). "The most crucial finding in this study was that PKC isoenzymes are robust biomarkers for the tumor immune status, PRKCB, PRKCH, and PRKCQ as stimulators, while PRKCI and PRKCZ as inhibitors in most cancers." (PMID 35174160, 2021). "And we found a significant difference in PRKCZ expression between cancer and normal samples (cancer mean 9.51, normal mean 7.75, p value = 0.0007)." (PMID 35174173, 2021). "The monoallelic loss was most prevalent in PRKCD, PRKCH, PRKCZ, and PRKCQ across different cancer types." (PMID 35174160, 2021). "Of the immune-related pathways, PD-L1 expression and PD-1 checkpoint pathway were highly correlated with all PKC genes among most cancers except PRKCZ." (PMID 35174160, 2021). "Protein kinase C iota (PKCι) and protein kinase C zeta (PKCζ) are two atypical protein kinase (aPKC) enzymes that contribute to cell proliferation and cancer development." (PMID 31412817, 2019). "HABP1 reportedly mediates cancer cell chemotaxis by interacting with PRKCZ on the cell membrane and regulates membrane translocation activity by organizing cell polarity and induces actin polymerization." (PMID 29535843, 2018). "In particular, SKI and PRKCZ in 1p36.33 have been reported to contribute to the loss function of TGFBR2 and SMAD4 in cancer." (PMID 26374103, 2015). "Additionally, PRKCZ participates in cell polarity pathways, and studies have illustrated that loss of cell polarity, which results in tissue disorganization, may contribute to cancer development." (PMID 25874946, 2015). "Moreover, a previous study revealed that the expression of TET2 and microRNA-200 is correlated, and their dysregulation can indirectly lead cancer stem cells to a luminal-cell-like state through the inhibition of protein kinase C zeta (PRKCZ)." (PMID 39201247, 2024). "In addition to the regulation of apoptosis, the protein products of these genes are involved in signaling pathways that are associated with cancer development and progression, including NF-ĸB (BCL3, SPHK1, and PRKCZ) and c-MYC (PIM1 and BTG1)." (PMID 38731835, 2024). "Thus, it is the first study to focus on the role of PRKCZ methylation in cancers, and a detailed mechanistic study is provided." (PMID 36077689, 2022). "Besides, PRKCD, PRKCH, PRKCZ, and PRKCQ were associated with varying degrees of low-level CNGs along with different cancers." (PMID 35174160, 2021). "Depending on our results, PRKCI, PRKCD, and PRKCZ associated-CNAs were driving their expressions in most cancers (except for PRKCI in DLBC, KICH, LAML, THCA, and THYM; PRKCD in GBM, HNSC, LAML, LGG, THYM, and UCS; and PRKCZ in ACC, GBM, KICH, LGG, THCA, THYM, and UCS)." (PMID 35174160, 2021). "Similar to PRKCZ, PRKCI belongs to the atypical protein kinase C family group, and it has been implicated in the establishment of cell polarity, motility, proliferation, and survival of cancer cells." (PMID 25874946, 2015). "The regulation of these pathways may explain some of the mechanisms by which PRKCZ can promote human cancers." (PMID 25874946, 2015). "The atypical protein kinase C isoform, PRKCZ, is involved in the control of various signalling processes including cell proliferation, cell survival, and cell motility, all of which are important for cancer development and progression." (PMID 25874946, 2015).
cancer (continued). "Genes PRKCZ (Protein Kinase C Zeta), FGR (Src family protein), KDM4B, MPO, COL11A1, FUT4 (Fucosyltransferase IV), and APEH (acylpeptide hydrolase) are directly associated with tumor aggressiveness, growth, and migration, and invasiveness, resulting in poor clinical outcome in cancer patients." (PMID 38086861, 2023). "However, evidence regarding the role of PRKCZ methylation in cancers remains limited." (PMID 36077689, 2022). "However, to the best of our knowledge, only one study has reported the role of PRKCZ in cancers." (PMID 36077689, 2022). "Furthermore, elevated PRKCZ levels generally might lower the response to immunotherapies in almost all cancers due to the inverted correlation with TILs, HLA genes, and PD-L1 expression." (PMID 35174160, 2021). "Indeed, the roles of PRKCZ in various cancer types have been examined in recent years." (PMID 25874946, 2015). "PRKCI and PRKCZ expressions were negatively correlated with most TILs in most cancer types (except PRKCI in ACC and OV; PRKCZ in ACC, SARC SKCM, had a positive correlation)." (PMID 35174160, 2021). "Another gene PRKCZ has not been tested to be efficient in treating this cancer, which may be potential targets for scientists and doctors to further research on it." (PMID 35174173, 2021). "CDK8, MET, PRKCZ, and PTK2 also exhibit negative scores against the majority of the cells, indicating inhibition of these hub genes could arrest cell proliferation required during cancer." (PMID 40500799, 2025).
tumor (18 papers, 2011 to 2024). "After drinking water with 4-NQO for 10 weeks followed by distilled water for an additional 10 weeks, PKC-ζ pseudosubstrate inhibitor and PRKCZ siRNA were injected near the tumor at 3-day intervals, and the mice were assessed after 3 weeks." (PMID 36077689, 2022). "PRKCZ acted as a potent tumor promoter in HNSCC by influencing DNA synthesis, holoprotein integrity and telomerase activity, and metastatic activity." (PMID 36077689, 2022). "In MDA‐MB‐231, we found a significant upregulation of LAPTM4B, RAB40C, MMP3, and downregulation of PRKCZ after tumor treatment with doxorubicin." (PMID 34109737, 2022). "Moreover, we suggest that PRKCZ plays a tumor-promoting role in HPV+ HNSCC via Cdc42, inhibiting E-cad expression, promoting N-cad and Vim expression, and finally contributing to EMT." (PMID 36077689, 2022). "Our results suggested that PRKCZ acted as a potential tumor promoter for HPV+ HNSCC." (PMID 36077689, 2022). "In addition, PRKCZ acts as a tumor promotor that induces HPV+ HNSCC cell proliferation, invasion, and migration and prevents apoptosis." (PMID 36077689, 2022). "In addition, blocking PRKCZ expression delayed the tumor growth of HPV16-E6/E7 transgenic mice." (PMID 36077689, 2022). "In addition, blocking PRKCZ delayed tumor growth in HPV16-E6/E7 transgenic mice." (PMID 36077689, 2022). "PRKCZ, a member of the PKC family, acts as a tumor suppressor by inhibiting the NF-κB signaling pathway; its dysregulation contributes to uncontrolled cell growth and resistance to apoptosis, thereby adversely affecting patient survival when underexpressed." (PMID 39064604, 2024). "We identified ALDH2 as a tumor suppressor in HCC, with three novel phosphorylation sites mediated by protein kinase C zeta that enhanced enzymatic activity." (PMID 38725845, 2024). "The tumor suppressor PTEN regulates CDC42 and apical PRKCZ activity that have a mechanistic role in spindle orientation, lumen formation and 3D epithelial morphology." (PMID 27119498, 2016). "Another three IL4 pathway genes (PRKCZ, PLCG1, PIK3CD) that were down-regulated with tumor progression showed further decreased expressions after chemotherapy in the current study." (PMID 23451142, 2013). "Transforming growth factor-β (TGF-β), fascin, nuclear factor-kappa B (NF-κB) p105, protein-kinase C-zeta (PKC-ζ), partioning-defective protein-6 (Par-6), E-cadherin and vimentin are tumor promoting molecules through mechanisms involved in cell dedifferentiation." (PMID 21390241, 2011).
infection (4 papers, 2013 to 2023). The state of being infected such as from the introduction of a foreign agent such as serum, vaccine, antigenic substance or organism. "Besides these three kinases, network enrichment analysis highlighted the general importance of kinases in infection development, e.g. JAK1, LYN, TYK2 and PRKCZ." (PMID 36579860, 2023).
PRKCZ also shares sentences with these, for which no sentence is quoted: glioma (2 papers); head and neck squamous cell carcinoma (2); lung carcinoma (2); adenocarcinoma of the (1); Anxiety (1); atherosclerosis (1); autism spectrum disorder (1); autoimmune disease (1); Autoimmunity (1); Behçet’s disease (1); benign recurrent intrahepatic cholestasis (1); brain diseases (1); cholangiocarcinoma (1); colon cancer (1); colorectal cancer (1); developmental delays (1); emphysema (1); endothelial dysfunction (1); epilepsy (1); gastrointestinal tumors (1); head and neck tumour (1); hematological malignancies (1); Hyperglycemia (1); hypersensitivity reactions (1); hyperuricemia (1); hypothyroidism (1); intestinal tumors (1); kidney cancer (1); left ventricular noncompaction (1); lung squamous cell carcinoma (1).
A further 15 diseases each share a sentence with PRKCZ in 1 paper.